CD63 (CD63 molecule)
Diseases named in the same sentence as CD63 in open-access papers (continued):
Sharing a sentence is not in itself a finding about the gene and the disease.
malaria (1 paper, 2023). Malaria is a serious and sometimes fatal disease caused by a parasite that commonly infects a certain type of mosquito which feeds on humans. "The signal intensities for capturing sEVs with the antibody cocktail against CD9, CD63, and CD81 and detecting them with unspecific IgG antibodies were similar in the two groups, indicating that the total amounts of released sEVs between malaria and healthy controls were comparable." (PMID 36961624, 2023).
mast cell leukemia (1 paper, 2021). Mast cell leukemia is a malignant form of systemic mastocytosis (SM) characterized, most of the time, by the presence of circulating mast cells. "In addition, midostaurin induced apoptosis and downregulation of CD2 and CD63 and inhibited IgE-dependent upregulation of CD63 in the mast cell leukemia cell line HMC-1, resulting in enhanced inhibition of cell growth." (PMID 34834162, 2021).
mastitis (1 paper, 2025). Inflammation of breast tissue during lactation or postpartum due to an obstructed duct or infection. "Three types of EVs (C-EVs, M-EVs, and CM-EVs) isolated from colostrum, mature milk, and clinical mastitis milk had similar double-layer membrane morphology consistent expression of marker proteins HSP70, TSG101, and CD63, but disparate particle diameters." (PMID 39953606, 2025).
meningioma (1 paper, 2013). A generally slow growing tumor attached to the dura mater. "Accordingly, TiMa from meningiomas with isolated monosomy 22/del(22q) showed increased expression levels of several activation-associated markers with higher percentages of CD69+ (p≤0.009 vs diploid and complex tumors) and CD63+ TiMa (p = 0.006 vs diploid cases)." (PMID 24098347, 2013).
mental disorder (1 paper, 2022). A disease that has its basis in the disruption of mental process. "In our preliminary experiments it was observed that serum levels of CD63+-EVs increased in sera of patients with various cancers, inflammatory diseases, and neurodegenerative/mental disorders." (PMID 35350978, 2022).
metastasis (1 paper, 2018). The spread or migration of cancer cells from one part of the body (where they first appeared) to another. "CD63 positivity in cancer cells was significantly correlated with scirrhous type (Type 4), tumor depth (T3-4), lymph node metastasis, lymphatic invasion, and tumor size (≥ 5 cm)." (PMID 30222750, 2018).
mood disorder (1 paper, 2022). A cognitive disorder a disturbance in which the person's mood is hypothesized to be the main underlying feature. "Four of our 16 candidate proteins have previously been investigated in relation to mood disorders or suicide (FKBP5, FGFR2, SCGB1A1, and CD63), but most candidate proteins are novel to mood disorders and suicide research." (PMID 35697758, 2022).
ocular toxoplasmosis (1 paper, 2024). Ocular toxoplasmosis is an infection in the eye caused by the parasite, Toxoplasm a gondii. "All plasma samples from patients with ocular toxoplasmosis and cataract were positivefor the tetraspanins CD63 and TSG101." (PMID 39109736, 2024).
osteomyelitis (1 paper, 2026). An acute or chronic inflammation of the bone and its structures due to infection with pyogenic bacteria. "We identified that significant infiltration of Arg1+Sdc4+, Cxcl1+Ccl4+, and Mif+Cd63+ macrophages may affect osteomyelitis through the Ccl3-Ccr1 and Cxcl2-Cxcr2 signaling pathways." (PMID 41836400, 2026).
ovarian cystadenoma (1 paper, 2018). A benign ovarian surface epithelial-stromal tumor characterized by the presence of cystic structures lined by serous epithelial cells, mucinous columnar epithelial cells, or endometrial-type well-differentiated cells. "Prior to quantification of exosomal miRNAs, extracted exosomes from two healthy women, one ovarian cystadenoma patient, and each two EOC patients at FIGO stage III and stage IV were verified on a western blot using antibodies specific for the exosomal marker CD63 and the miRNA binding protein AGO2." (PMID 30107086, 2018).
Parkinson's disease dementia (1 paper, 2024). "Moreover, multiplex analysis of single exosomes from the CSF of Parkinson's disease dementia (PDD) patients via solid-state technology revealed various surface markers, such as CD9, CD63, and CD81." (PMID 39431275, 2024).
pneumonia (1 paper, 2024). An acute, acute and chronic, or chronic inflammation focally or diffusely affecting the lung parenchyma, caused by an infection in one or both of the lungs (by bacteria, viruses, fungi, or mycoplasma.). "Considering the heterogeneity of BALF exosomes from the different individuals, the percentage of SCIMP+ particles in CD63+ particles was analyzed; this percentage was significantly higher in the pneumonia cohort than in the pulmonary tumor cohort, and the AUC of the ROC curve was 0.84." (PMID 38263143, 2024).
prostate adenoma (1 paper, 2017). "Royo and co-workers could also observe different TSG101 levels in different samples from prostate adenoma patients with relatively equal CD63 protein levels, considering different exosomal protein loading as a possible reason." (PMID 28859135, 2017).
pseudoexfoliative glaucoma (1 paper, 2024). "Previous research observed in patients with pseudoexfoliative glaucoma also noted the highest number of exosomes detected using antibodies targeting CD63 among tetraspanin complexes." (PMID 38920659, 2024).
rectal adenocarcinoma (1 paper, 2021). "The impact of NCCR on CD63 and CD9 expression and their prognostic significance in patients with rectal adenocarcinoma is yet to be explored." (PMID 34316329, 2021). "The impact of neoadjuvant concurrent chemoradiation (NCCR) on exosomal markers (CD63 and CD9) expression and their prognostic significance in patients with rectal adenocarcinoma are yet to be explored." (PMID 34316329, 2021). "Using IHC, the exosomal markers (CD63 and CD9) expression increased in patients with rectal adenocarcinoma after treatment with NCCR and thus suggest a possible role of these exosomes in adaptive response to NCCR." (PMID 34316329, 2021).
renal carcinoma (1 paper, 2022). A carcinoma arising from the epithelium of the renal parenchyma or the renal pelvis. "We first detected the expression of CD63 (exosomes marker) by IHC in tissues from renal cancer." (PMID 35646637, 2022).
renal fibrosis (1 paper, 2023). A final common manifestation of a wide variety of chronic kidney diseases characterized by glomerulosclerosis and tubulointerstitial fibrosis. "Time-course study revealed that TNFAIP8 started to increase as early as day 1 in UUO models, and continued to increase along with the progression of renal fibrosis, which was concomitant with CD63 induction." (PMID 37828075, 2023).
respiratory allergy (1 paper, 2024). "In a subsequent study of 53 children with respiratory allergy with SPT used as the “gold standard”, the sensitivity of the BAT (CD63+) was 96.9% and the specificity was 88.9% for D. pteronyssinus, with respective values of 89.3% and 100% for D. farinae." (PMID 39337447, 2024).
Salmonella Infections (1 paper, 2024). Infections with bacteria of the genus SALMONELLA. "We have previously identified that GW4869 inhibitor of N-SMase did reduce the number of CD63-positive EVs (likely exosomes) during Salmonella infection of human macrophages." (PMID 38078720, 2024).
schwannoma (1 paper, 2022). A benign, usually encapsulated slow growing tumor composed of Schwann cells. "CD163: Schwannomas were positive for CD63, with high intensity in all sections, while GCT immunoreactivity was absent." (PMID 35323240, 2022).
sensitization (1 paper, 2024). "Previous studies demonstrated that CD63 expression and spontaneous basophil activation were significantly higher in CU patients with allergic sensitization than in children without it, suggesting that allergic sensitization may be an underlying factor contributing to the pathogenesis of CU." (PMID 38255399, 2024).
soft tissue sarcoma (1 paper, 2017). A malignant neoplasm arising from muscle tissue, adipose tissue, blood vessels, fibrous tissue, or other supportive tissues excluding the bones. "Thus, further studies need to be carried out assessing the prognostic value of high CD62P- and CD63-positive microvesicle counts with the occurrence of VTE as well as the outcomes of LMWH use for thromboprophylaxis in patients with soft tissue sarcoma." (PMID 28784104, 2017). "Thus, we assume that the risk of VTE in patients with soft tissue sarcoma is not related to the release of TF-bearing microvesicles but rather to other factors such as the elevation of CD62P- and CD63-positive microvesicles." (PMID 28784104, 2017).
steatosis (1 paper, 2024). Increased lipid within the cytoplasm of cells. "CD63, C-Type Lectin Domain Family 1 Member B (CLECB1), CD38, MANF, and Gamma-interferon-inducible lysosomal thiol reductase (IFI30) were all associated with steatosis grade in PWS." (PMID 39407757, 2024). "In this group, CD63 and CD38 positively correlated with steatosis grade, while NCAN and BCAN positively correlated with bioimpedance values." (PMID 39407757, 2024).
thrombus (1 paper, 2005). "A significantly higher level of circulating platelets expressing P-selectin and CD63 and more leukocyte-platelet conjugates were found in patients positive for both SEC and left atrial thrombus or embolic events." (PMID 15733325, 2005).
thyroid (1 paper, 2025). "Does the expression of CD63 in extracellular vesicles present in serum differ between thyroid pathologies?" (PMID 41551612, 2025). "CD63 expression varied between thyroid pathologies, in contrast to earlier tissue-on-chip studies that used nanoparticle tracking analysis, which does not assess marker expression." (PMID 41551612, 2025).
toxoplasmosis (1 paper, 2024). A parasitic disease contracted by the ingestion or fetal transmission of toxoplasma gondii. "However, the aqueous humor from patients withocular toxoplasmosis was positive only for CD63." (PMID 39109736, 2024).
xanthoma (1 paper, 2025). A non-neoplastic disorder characterized by a localized collection of histiocytes containing lipid. "These xanthoma cells contain plenty of lipids, and CD68, CD163, and CD63 are positive in immunohistochemistry, indicating a macrophage phenotype." (PMID 40502883, 2025).
tumor (311 papers, 2004 to 2026). "Secondly, double glycosylated TIMP-1 was the most efficient TIMP-1 variant to interact with CD63, promoting tumor cell proliferation and survival." (PMID 40345589, 2025). "Single-cell transcriptomic analysis identified a CD63-high tumor subpopulation in UM associated with lactate metabolism and vesicle transport." (PMID 41573746, 2025). "For example, conserved Gpnmb RecAM genes (e.g., Cd63, Fabp5, Lgals3, and Gpnmb) are hallmarks of lipid-associated macrophages found in the tumor microenvironment and chronically inflamed liver and adipose tissue." (PMID 39509324, 2024). "Expression of the well-accepted exosome marker proteins, CD9, CD63, and Tumor Susceptibility Gene 101 (TSG101), were identified by western blot." (PMID 36697384, 2023). "CD63/81+ sEVs significantly populated diagnostic AH from most advanced group E eyes and those eyes which required surgical removal due to massive tumor involvement or treatment resistance." (PMID 37410475, 2023). "CD9 and CD63 have been reported to associate with the metastatic ability of tumor cells, such that higher expression promotes decreased cell motility." (PMID 37355988, 2023). "Surface values of immune checkpoints and tumor associated antigens on saliva-derived exosomes were analyzed by bead-based flow cytometry using CD63 capture." (PMID 35899209, 2022). "CD9, CD63, or glypican-1 can be taken into consideration as generic tumor-associated markers of exosomes produced by a major group of cancers." (PMID 35757760, 2022). "Multicomparison studies also revealed that the expression of CD9 was associated with tumor size, whereas CD63 upregulation was associated with histological diagnosis and vascular invasion." (PMID 34065085, 2021). "In cancer, the surface expression of CD63 is linked to tumor cell motility, and a decrease of this tetraspanin is linked to the increased malignancy and higher chances of metastasis." (PMID 33669943, 2021). "Although the secretion of CD81+CD63+EVs from 67NR clones caused an increase in proliferation and migration in vitro, the tumor growth was inhibited in vivo." (PMID 34503207, 2021). "More importantly, emerging evidences have implicated a correlation between abnormal CD63 expression and tumour progression." (PMID 33277798, 2021). "Lower CD63 expression was significantly associated with larger tumour size (P < .05), distant site metastasis (P < .01) and higher TNM stage (P < .01)." (PMID 33277798, 2021). "CD63 expression in tumor-associated microglia/macrophages was examined by double-immunofluorescence with ionized calcium-binding adapter molecule 1 (Iba1)." (PMID 29523123, 2018). "ADMSC-derived exosomes appeared as nanoparticles (30–90 nm) on electron microscopy and were positive for CD63, tumor susceptibility gene-101, and β-catenin on western blotting." (PMID 26345219, 2015). "Vesicles were isolated by differential centrifugations and analysed for their expression of CD63, tumour-associated antigens and HLA-A2 molecules by flow cytometry of exosome-coated latex beads and Western blot." (PMID 26082317, 2013). "We designed an in-house sandwich ELISA (Exotest) to capture and quantify exosomes in plasma based on expression of housekeeping proteins (CD63 and Rab-5b) and a tumor-associated marker (caveolin-1)." (PMID 19381331, 2009). "Furthermore, the expression of the typical markers including heat shock protein 70 (HSP70), CD63, and tumor susceptibility hum 101 (TSG101) were detected by WB analysis." (PMID 34838052, 2021). "Furthermore, high levels of CD63, as found in this study, are associated with the mediation of tumour progression and the EMT, being elevated in cancer patients." (PMID 33923802, 2021).
tumor (continued). "GFP imaging in excised HCC tissues revealed directional transfer of CD63-GFP+ EVs from the right to the left tumor." (PMID 41362734, 2026). "This demonstrates that TIMP-1 glycosylation is not necessary for the execution but rather for the modulation of the antiproteolytic activity of TIMP-1, while glycosylation was necessary to execute the tumor-promoting cytokine-like effects of TIMP-1 via CD63." (PMID 40345589, 2025). "Koumangoy and colleagues used CD63-GFP expressing cancer cells to investigate the role of exosomes in tumour biology." (PMID 41304773, 2025). "For instance, PLA2G2A+ CAFs can regulate tumorigenesis by modulating tumor metabolism, while CD63+ CAFs strengthen the drug tolerance of tumor cells." (PMID 40855046, 2025). "To accomplish this, we performed LAMP1 and CD63 immunostaining on tumor biopsies collected from the same patients before and after treatment." (PMID 39930269, 2025). "An example is the bispecific HER2 ˟ CD63his-ADC, which recognizes HER2 and CD63, facilitating improved internalization and anti-tumor efficacy of HER2-targeted ADCs." (PMID 39990653, 2025). "This antibody binds to HER2-expressing cancer cells through its anti-HER2 arm, whereas its second arm attaches to CD63, directing endocytosis-mediated transport of the drug payload directly to tumor cells, resulting in their destruction." (PMID 39990653, 2025). "The western blotting analysis showed that the isolated exosomes from BNT162b2-transfected tumor cells carried not only exosome markers CD63 and TSG101, but also the SARS-CoV-2 spike protein and OVA protein." (PMID 39743545, 2025). "First, tumor-derived CD63-positive exosomes enter platelets leading to platelet activation, which further promotes tumor progression." (PMID 40948741, 2025). "In an animal model of Ewing sarcoma, ENO-1+ CD63+ EVs were elevated along with tumor growth and reduced after tumor resection." (PMID 40679665, 2025). "Subsequently, we found that CD63/81+ sEVs were abundant in pre-treatment RB eyes, particularly those with higher tumor burden, suggesting CD63/81+ sEVs are tumor-derived, showcasing their potential as biomarkers." (PMID 39519212, 2024). "CD63/81+ sEVs were notably abundant in pre-treatment RB eyes, especially those with higher tumor burden, indicating their potential as tumor-derived biomarkers." (PMID 39519212, 2024). "For this purpose, a cancer KPF CD63-phyYFP cell line was created from a KPF CD63-mCherry tumor, as detailed in the Methods section." (PMID 38383468, 2024). "We demonstrated that paclitaxel treatment in both EO771 and 4T1-GFP tumor-bearing mice resulted in increased CD63 levels compared to mice receiving vehicle." (PMID 38405101, 2024). "Plasma was isolated from the blood of tumor-bearing mice with tumors of similar size to examine changes in circulating TEVs using anti-CD63 ELISA." (PMID 38405101, 2024). "Conversely, Tspan7, CD82, CD63, Tspan7, and Tspan9 are downregulated, suppressing digestive system tumor cell metastasis." (PMID 38389703, 2024). "On the other hand, CD63, which we found to be enriched in hTERT-immortalized MSC EVs, has been associated with tumor suppression and decreased invasiveness." (PMID 38786083, 2024). "This indicates that to conduct species-specific EV purifications, additional anti-human anti-CD63 antibodies will have to be tested to guarantee sole purification of human tumor EVs from mouse EBC." (PMID 38863869, 2024). "The strong and consistent expression of CD63 across all EV samples derived from the cultured tumor model suggests the presence of exosomes." (PMID 39594703, 2024). "Subsequently, we also revealed the colocalization of PD-L1 with CD63, a marker protein of sEVs, by immunofluorescence staining in tumour cells and found that it was promoted after the treatment with aT-sEVs, suggesting the enhanced secretion of PD-L1 via sEVs." (PMID 38719909, 2024).